RNU6-76P (RNA, U6 small nuclear 76, pseudogene)
Synonyms: RNU6-1002P; RNU6-76
Gene: Small nuclear RNA gene on chromosome 13 (18,880,054 to 18,880,157, forward strand). Ensembl gene ENSG00000206787.
Homologues: Orthologues: chimpanzee U6 (100% identical), chimpanzee U6 (99% identical), macaque U6 (86% identical), rat U6 (85% identical). Paralogues in human: RNU6-331P (91% identical), RNU6-1235P (90% identical), RNU6-498P (90% identical), U6 (90% identical), RNU6-1158P (88% identical), RNU6-25P (88% identical), RNU6-33P (88% identical), RNU6-38P (88% identical), RNU6-476P (88% identical), RNU6-574P (88% identical), RNU6-1 (88% identical), RNU6-1029P (88% identical), and 1283 more.